ENSG00000253143 (novel transcript)
Gene: Long non-coding RNA gene on chromosome 8 (70,471,112 to 70,480,623, reverse strand). Ensembl gene ENSG00000253143.
Gene Ontology:
Biological process: SRP-dependent cotranslational protein targeting to membrane, signal sequence recognition
Cellular component: signal recognition particle, endoplasmic reticulum targeting